OR8B2 (olfactory receptor family 8 subfamily B member 2)
Description:
Odorant receptor.
Synonyms: OR11-309; OR11-310
Tractability: Antibody: UniProt places it where antibodies can reach, with medium confidence; UniProt predicts a signal peptide or a membrane-spanning region; its Gene Ontology location is reachable by antibodies, with medium confidence.
Gene: Protein-coding gene on chromosome 11 (124,382,394 to 124,384,499, reverse strand). Ensembl gene ENSG00000284680.
Subcellular location: Cell membrane
Pathways (Reactome):
Sensory Perception: Expression and translocation of olfactory receptors
Gene Ontology:
Molecular function: olfactory receptor activity; G protein-coupled receptor activity
Biological process: G protein-coupled receptor signaling pathway; sensory perception of smell; detection of chemical stimulus involved in sensory perception of smell
Cellular component: plasma membrane; membrane
Genetic constraint (gnomAD): Loss-of-function variants: 0 observed, 0.39 expected, observed/expected ratio (o/e) 0, 90% interval 0 to 1.85. That is too few expected variants to judge how well the gene tolerates losing a copy. Missense variants: 304 observed, 359.09 expected, observed/expected ratio (o/e) 0.85, 90% interval 0.77 to 0.93. Synonymous variants: 98 observed, 130.33 expected, observed/expected ratio (o/e) 0.75, 90% interval 0.64 to 0.89.
Homologues: Orthologues: chimpanzee OR8B2 (97% identical), dog OR8B3 (89% identical), rat Or8b3 (83% identical), rat Or8b3c (83% identical), mouse Or8b3 (82% identical), mouse Or8b3b (79% identical). Paralogues in human: OR8B3 (98% identical), OR8B8 (70% identical), OR8B12 (68% identical), OR8B4 (67% identical), OR8G1 (65% identical), OR8G5 (63% identical), OR8A1 (62% identical), OR8G3 (61% identical), OR8G2P (60% identical), OR8D2 (58% identical), OR8D1 (58% identical), OR8D4 (58% identical), and 84 more.